FLNB (filamin B)
Description:
Connects cell membrane constituents to the actin cytoskeleton. May promote orthogonal branching of actin filaments and links actin filaments to membrane glycoproteins. Anchors various transmembrane proteins to the actin cytoskeleton. Interaction with FLNA may allow neuroblast migration from the ventricular zone into the cortical plate. Various interactions and localizations of isoforms affect myotube morphology and myogenesis. Isoform 6 accelerates muscle differentiation in vitro.
Synonyms: FLN-B; Fh1; FLN1L; TABP; TAP; ABP-278; ABP-280; LRS1
Tractability: Small molecule: it has a binding pocket of medium quality. Antibody: its Gene Ontology location is reachable by antibodies, with high confidence; the Human Protein Atlas places it where antibodies can reach. PROTAC: UniProt records ubiquitination sites on it; ubiquitination databases record sites on it; its protein half-life has been measured.
Target class: Structural protein
Gene: Protein-coding gene on chromosome 3 (58,008,398 to 58,172,251, forward strand). Ensembl gene ENSG00000136068.
Subcellular location: Cytoplasm, cell cortex (Isoform 1); Cytoplasm, cytoskeleton; Cytoplasm, cytoskeleton, stress fiber; Cytoplasm, myofibril, sarcomere, Z line; Cytoplasm, cytoskeleton, stress fiber (Isoform 2); Cytoplasm, cytoskeleton, stress fiber (Isoform 3); Cytoplasm, cytoskeleton (Isoform 6)
Subcellular location (Human Protein Atlas): Plasma membrane; Actin filaments; Cytosol; Golgi apparatus
Pathways (Reactome):
Immune System: ISG15 antiviral mechanism
Gene Ontology:
Molecular function: cadherin binding; identical protein binding; protein binding; RNA binding; actin binding; actin filament binding
Biological process: actin cytoskeleton organization; signal transduction
Cellular component: cytoplasm; cytosol; extracellular exosome; focal adhesion; plasma membrane; actin cytoskeleton; membrane; brush border; cell cortex; cytoskeleton; phagocytic vesicle; stress fiber; Z disc
Genetic constraint (gnomAD): Loss-of-function variants: 107 observed, 249.51 expected, observed/expected ratio (o/e) 0.43, 90% interval 0.37 to 0.5. The upper end of that interval is the gene's LOEUF score, 0.5, which puts it in group 2 of 6, group 1 being the genes least tolerant of losing a copy. Missense variants: 2,865 observed, 3,613.8 expected, observed/expected ratio (o/e) 0.79, 90% interval 0.77 to 0.82. Synonymous variants: 1,297 observed, 1,437.7 expected, observed/expected ratio (o/e) 0.9, 90% interval 0.86 to 0.94.
Gene-disease validity (ClinGen):
ClinGen rates the evidence that FLNB causes each of these diseases.
FLNB-associated autosomal dominant filamin related bone disorder (autosomal dominant): Definitive. Any autosomal dominant filamin related bone disorder in which the cause of the disease is a variation in FLNB gene.
Homologues: Orthologues: chimpanzee FLNB (99% identical), macaque FLNB (99% identical), dog FLNB (98% identical), pig FLNB (98% identical), guinea pig FLNB (96% identical), mouse Flnb (96% identical), rat Flnb (96% identical), rabbit FLNB (95% identical), tropical clawed frog flnb (80% identical), zebrafish flnbl (50% identical), Drosophila melanogaster CG5984 (4% identical), zebrafish flnbl (4% identical). Paralogues in human: FLNC (71% identical), FLNA (70% identical), MACF1 (15% identical), DST (14% identical), PLEC (14% identical), SPTB (13% identical), SPTBN1 (13% identical), SYNE1 (12% identical), SPTBN4 (11% identical), SPTBN2 (11% identical), SYNE2 (11% identical), SPTBN5 (11% identical), and 24 more.
Diseases named in the same sentence as FLNB in open-access papers:
FLNB is named in the same sentence as 108 diseases in open-access papers, as found by Europe PMC text mining. Sharing a sentence is not in itself a finding about the gene and the disease. The quoted sentences say what the papers report.
Larsen syndrome (24 papers, 2010 to 2025). A rare skeletal dysplasia characterized by congenital dislocation of large joints, foot deformities, cervical spine dysplasia, scoliosis, spatula-shaped distal phalanges and distinctive craniofacial abnormalities, including cleft palate. "A 24-repeat encoding-region of FLNB is essential for the formation of Filamin B dimers, and the majority of heterozygotic pathogenic variants associated with Larsen syndrome cluster in this repeat region or in the actin-binding domain." (PMID 41062856, 2025). "Intrinsic or genetic factors are also implicated, such as in Larsen syndrome, which occurs in about 1 per 100,000 live births and is linked to mutations in the filamin B gene." (PMID 39864215, 2025). "Pathogenic variants in the FLNB gene are associated with Larsen syndrome (autosomal-dominant inheritance), primarily with missense variants rather than loss-of-function (LoF) variants." (PMID 41244983, 2025). "A case-study including a 63-year-old women and her 33-year-old daughter with Larsen syndrome, both carrying a novel FLNB c.688G > T, p.(Val230Phe) variant." (PMID 41062856, 2025). "Another heterozygous missense variant (p.Gln685His), identified in the gene FLNB in monozygotic twins, was characterized as likely pathogenic and associated with Larsen syndrome." (PMID 38929227, 2024). "Larsen syndrome is caused by heterozygous pathogenic variants in FLNB and is inherited in an autosomal dominant manner." (PMID 37433679, 2023). "High-throughput sequencing focused on clinically significant variants in genes associated with hereditary cancer, connective tissue disorders including FLNB (which is associated with Larsen syndrome), and carotid dissection." (PMID 37433679, 2023). "Similar duplicate calcaneus is observed in an infant with Larsen syndrome, which is caused by heterozygous mutations in the filamin B gene (FLNB)." (PMID 32887348, 2020). "This case study will examine an atypical presentation of Larsen syndrome in which a family has a classic pathogenic FLNB variant with an autosomal dominant mode of inheritance, but is lacking the typical associated hallmark joint dislocations." (PMID 30916490, 2019). "The E227K variant in the FLNB gene has been reported in association with Larsen syndrome, as both a de novo variant and an inherited variant." (PMID 30916490, 2019). "Heterozygous pathogenic variants in FLNB account for the majority of patients with Larsen syndrome; however, recently discovered homozygous pathogenic variants in CHST3 (OMIM 603799) and B4GALT7 (OMIM 604327) confirm the existence of recessive forms." (PMID 30916490, 2019). "No pathogenic or unclassified variant was identified in the gene for autosomal dominant Larsen syndrome, FLNB." (PMID 30170566, 2018). "We report the case of a male patient with Larsen syndrome found to be mosaic for a novel point mutation in FLNB in whom it was possible to provide evidence‐based personalized counseling on transmission risk to future offspring." (PMID 28639312, 2017). "Larsen syndrome (MIM# 150250) is an autosomal‐dominant congenital osteochondrodysplasia caused by mutations in the filamin B gene (FLNB)." (PMID 28639312, 2017). "This residue is located within the second calponin homology domain 2 (CHD2) of the filamin B protein, a known hotspot region for Larsen syndrome mutations." (PMID 28639312, 2017). "Mutations in human FLNB have been found in various skeletal disorders with vertebral abnormalities, including spondylocarpotarsal synostosis, boomerang dysplasia, Larsen syndrome, and atelosteogenesis III." (PMID 23979929, 2013). "Another example is Larsen Syndrome, caused by mutations in filamin B, where individuals can display kyphosis; however, other symptoms of the disease include dislocation of the knees, flat facial features, and cylindrical-shaped fingers." (PMID 21176156, 2010).
Larsen syndrome (continued). "Specific heterozygous FLNB variants cause Larsen Syndrome, while others result in lethal forms of osteochondrodysplasias, such as atelosteogenesis types I and III, and boomerang dysplasia, which are characterized by the absence or under-ossification of limb bones and vertebrae." (PMID 41062856, 2025). "Here, we report a new FLNB variant in two women with Larsen syndrome and provide a detailed description of their skeletal phenotype, which is characterized by low spinal and hip BMD, as well as reduced trabecular bone volume, trabecular number, and cortical thickness." (PMID 41062856, 2025). "However, some cases of recessive Larsen syndrome can also be linked to mutations in genes other than FLNB, for example, CHST3 (OMIM:603799)." (PMID 37565102, 2023). "FLNB is important for fetal skeletal development and FLNB mutations are associated with atelosteogenesis I, Larsen syndrome, and spondylocarpotarsal synostosis syndrome, a disease of ectopic ossification that causes inappropriate fusion of the bones of the vertebrae, wrists, and ankles." (PMID 29567674, 2018). "We originally identified a spontaneous mutation in FLNB (c.698A>G, encoding p.(Tyr233Cys)) that was detected at low level on dideoxy sequencing traces in DNA sampled from buccal cells and dermal fibroblasts of a Larsen syndrome patient." (PMID 28639312, 2017). "Biallelic FLNB variants have been reported in a 46,XY DSD individual with female external genitalia and skeletal dysplasia, and are implicated in Larsen syndrome (OMIM:150,250), which is associated with cryptorchidism." (PMID 40037090, 2025). "Larsen syndrome is caused by mutations in the FLNB gene, which encodes the cytoskeletal protein filamin B, crucial in the development of the skeleton." (PMID 37565102, 2023). "Mutations of filamin B (FLNB) gene can lead to a spectrum of autosomal skeletal malformations including spondylocarpotarsal syndrome (SCT), Larsen syndrome (LRS), type I atelosteogenesis (AO1), type III atelosteogenesis (AO3), and boomerang dysplasia (BD)." (PMID 35832491, 2022). "Larsen syndrome is caused by mutations in the FLNB gene (OMIM 603381), which encodes the connective tissue protein, filamin B. This protein is thought to be involved in vertebral segmentation, joint formation, and endochondral ossification." (PMID 30916490, 2019). "Molecular interactions between FLNB and SMADs signaling in skeletal morphogenesis may lead to similar phenotypes of ossifications in the calcaneal region in Larsen syndrome and FOP." (PMID 32887348, 2020). "FLNB-related osteogenesis imperfecta type I/Larsen syndrome is an autosomal dominant disease." (PMID 31299979, 2019). "Mutations in the FLNB (filamin B; MIM 603381) gene cause a group of skeletal dysplasias comprising spondylocarpotarsal syndrome (SCT, MIM 272460), Larsen syndrome (LS, MIM 150250), atelosteogenesis I and III (AOI, MIM 108720; AOIII, MIM 108721), and boomerang dysplasia (BD, MIM 112310)." (PMID 27048506, 2016). "FLNB (filamin B) plays a role in the spondylocarpotarsal synostosis (SCT) syndrome, Larsen syndrome, atelosteogenesis types I and III (AOI and AOIII), and Piepkorn osteochondrodysplasia (POCD), which are also associated with the bone disorders." (PMID 36005137, 2022). "FLNB is a cytoskeletal protein that plays a key role in bone morphogenesis; however, the skeletal phenotype of Larsen syndrome has not been described in detail." (PMID 41062856, 2025).
breast carcinoma (9 papers, 2018 to 2024). "We previously identified an alternative splicing change in FLNB that favors a variant promoting the mesenchymal state in human breast cancer." (PMID 38753413, 2024). "Moreover, skipping of FLNB exon 30 is strongly associated with EMT gene signatures in basal-like breast cancer patient samples." (PMID 30059005, 2018). "Alternative splicing of FLNB exon 30 is strongly associated with basal-like breast cancer." (PMID 30059005, 2018). "Since mesenchymal and stem-like cell features are enriched in basal-like breast cancer, we examined whether the splicing of FLNB and the expression of QKI or RBFOX1 were associated with the basal-like subtype in TCGA Breast Invasive Carcinoma (BRCA) samples." (PMID 30059005, 2018). "CRISPR-mediated deletion of FLNB exon 30 from the genome of breast cancer cells is sufficient to convert breast cancer cells from an epithelial to a mesenchymal phenotype." (PMID 37752235, 2023). "Increased skipping of FLNB exon 30 (an exon normally activated by the AR-ESRP axis in prostate cancer), is tightly linked to the development of metastases in breast cancer." (PMID 37752235, 2023). "Although it is not differentially spliced between normal prostate and prostate cancer, increased skipping of FLNB exon 30 has been recently reported as a key driver of EMT in breast cancer development." (PMID 31478829, 2019). "In breast cancer, the metastatic effects of FLNB alternative splicing are mediated via the FOXC1 transcription factor." (PMID 31478829, 2019). "Among all the common targets of QKI and RBFOX1, we found that CD44 (IC:0.857, p value:<6.59e-07) and FLNB (IC:0.848, p value:<6.59e-07) scored as the top two genes that most strongly associated with the EMT signature in breast cancer cell lines." (PMID 30059005, 2018). "This switching between different FLNB proteins happens in some of the more aggressive breast cancers, which also contain mesenchymal cells." (PMID 30059005, 2018). "Here, we found that QKI and RBFOX1 regulate the splicing of an exon in the actin-binding protein FLNB to regulate the EMT in breast cancer." (PMID 30059005, 2018). "We further found that there is a strong association between the AS of FLNB exon 30 and EMT gene expression features in breast cancer cell lines." (PMID 30059005, 2018). "In addition, we document an inverse relationship between RNA editing at splice sites or ADAR2 expression and the alternative splicing in Filamin B (FLNB), which was shown to be associated with epithelial to mesenchymal phenotype in breast cancer." (PMID 36221913, 2022). "Skipping of FLNB exon 30 is sufficient to initiate metastatic progression in breast cancer." (PMID 31478829, 2019). "Another example is the gene FLNB whose exon 30 was found to be skipped in the majority of tumors, which is consistent with previous findings that the skipping of this exon induces EMT, is associated with basal-like breast cancer, and is regulated by the RNA binding proteins QKI and RBFOX1." (PMID 38674106, 2024). "While some of the top candidates have been previously reported to play a role in cancer (FLNB, MAP3K7, NFYA, and ESYT2) others were identified to be breast cancer-relevant for the first time (NEDD4L, MARK2, ABI1)." (PMID 38664594, 2024). "For instance, ES in FLNB has been reported to promote EMT in breast cancer by releasing the FOXC1 transcription factor and reducing FLNB nuclear localization." (PMID 34326872, 2021). "We found several targets of QKI and RBFOX1, including FLNB, SLK, USO1, ENAH, ESYT2, NUMB and ARHGEF1, to be among the most differentially spliced genes in basal B breast cancer cell lines." (PMID 30059005, 2018).
Boomerang dysplasia (8 papers, 2013 to 2022). A rare lethal skeletal dysplasia characterized by severe short-limbed dwarfism, dislocated joints, club feet, distinctive facies and diagnostic x-ray findings of underossified and dysplastic long tubular bones, with a boomerang-like bowing. "We detected a pathogenic variant in sample F10177-2 located at the FLNB gene (NM_001457:c.605T > C:p.M202T), and associated with a lethal form of SD (Ateleosteogenesis type 1/Boomerang dysplasia)." (PMID 30043834, 2018).
spondylocarpotarsal syndrome (7 papers, 2014 to 2022). "Humans who harbor loss of function mutations in the actin-associated filamin B (FLNB) gene develop spondylocarpotarsal syndrome (SCT), a disorder characterized by dwarfism (delayed bone formation) and premature fusion of the vertebral, carpal and tarsal bones (premature differentiation)." (PMID 24551245, 2014). "Null alleles of FLNB cause recessive spondylocarpotarsal syndrome (SCT; OMIM 272460), which features dwarfism and fusion of the vertebral, carpal, and tarsal bones." (PMID 24551245, 2014). "Spondylocarpotarsal syndrome (SCT) is a rare musculoskeletal disorder characterized by short stature and vertebral, carpal, and tarsal fusions resulting from biallelic nonsense mutations in the gene encoding filamin B (FLNB)." (PMID 35474298, 2022).
Spondylocarpotarsal synostosis (7 papers, 2013 to 2025). "FLNB encodes filamin B, a cytoplasmic protein that organizes the actin cytoskeleton, whose alterations cause skeletal disorders, including AD Larsen syndrome and AR spondylocarpotarsal synostosis." (PMID 41210864, 2025). "The loss of Filamin B, a protein component of the cell’s cytoskeletal structure, gives rise to Spondylocarpotarsal Synostosis, a rare genetic disorder characterized by fusions of the vertebral bodies." (PMID 27019229, 2016). "Spondylocarpotarsal synostosis (SCT) syndrome is a recessively inherited disorder caused by nonsense mutations in Filamin B (FLNB); it is characterized by progressive vertebral, carpal, and tarsal bone fusions, short stature, and scoliosis." (PMID 27019229, 2016). "Spondylocarpotarsal synostosis (SCT) is an autosomal recessive disorder characterized by progressive vertebral fusions and caused by loss of function mutations in Filamin B (FLNB)." (PMID 27019229, 2016).
prostate carcinoma (6 papers, 2017 to 2025). A carcinoma that arises from epithelial cells of the prostate gland. "Filamin-B (FLNB) was identified as biomarkers in a strategy for prostate cancer (PrCa) biomarker discovery." (PMID 34150649, 2021). "This study reports on the development of a novel serum protein panel of three prostate cancer biomarkers, Filamin A, Filamin B and Keratin-19 (FLNA, FLNB and KRT19) using multivariate models for disease screening and prognosis." (PMID 29682400, 2017). "Among these genes, high expression of certain genes, such as FLNA and DSTN, is positively correlated with the prognosis of prostate cancer patients, while elevated expression of other genes, including FLNB and INF2, is associated with a negative prognosis." (PMID 41049007, 2025). "The upregulated gene set included oncogenes such as PIK3CB, FGFRL1, and NCOA2; prostate cancer-related genes such as SPON2, PCAT4, and SCHLAP1; and cell cycle genes such as MKI67, MCM4, KIF4A, CENPF, and FLNB." (PMID 38067373, 2023). "A recent study by this group discovered three novel biomarkers, FLNA, FLNB and KRT19 for prostate cancer." (PMID 29682400, 2017). "FLNB and Keratin-19 (KRT19) were identified as very important nodes that were causally influenced by culture conditions of hypoxia and lactic acid in the metastatic prostate cancer cell line, PC-3." (PMID 28344825, 2017).
Hypertension (4 papers, 2022 to 2023). The presence of chronic increased pressure in the systemic arterial system. "FLNA rs2070816 (CT + TT vs. CC) and rs2070829 (CG + GG vs. CC) were significantly associated with the hypertensive status in young subjects (<55 years group) and FLNB rs839240 (AG + GG vs. AA) was significantly associated with hypertension in females." (PMID 36672629, 2023). "Chunlan Liu and colleagues explored the associations of Filamin A (FLNA) and Filamin B (FLNB) variants with hypertension." (PMID 36672629, 2023). "Recently, it was observed that FLNB, which is thought to be a dimeric actin-binding protein that is implicated in skeletal deformities, plays a role in platelet dysfunction and hypertension; however, very little is known regarding its role in PE." (PMID 35711567, 2022). "Further mechanistic studies defining changes in FLNB expression, post-translational modification, and protein interactions in the context of preeclampsia will clarify its contributions to this complex hypertensive disorder of pregnancy." (PMID 38099221, 2023). "Moreover, based on the decreased A-to-I editing rate of myocardial filamin B, the authors hypothesized filamin B editing to play a still-hidden function in cardiovascular system, similarly as filamin A (FLNA) has been unveiled in hypertension." (PMID 35991314, 2022).